MFN2 (mitofusin 2)
Diseases named in the same sentence as MFN2 in open-access papers (continued):
Sharing a sentence is not in itself a finding about the gene and the disease.
thyroid cancer (3 papers, 2021 to 2023). "In this study, we evaluated the role of MFN2 only using the RAS mutated thyroid cancer cells (Cal62 and HTH83) originated from anaplastic thyroid carcinoma." (PMID 33479369, 2021). "Taken together, these results suggest that MFN2 plays an important role in thyroid cancer progression, and that low MFN2 expression is significantly associated with tumor aggressiveness in human thyroid cancer." (PMID 33479369, 2021). "TCGA analysis revealed that MFN2 expression was lower in thyroid cancer than in normal tissues and significantly associated with a degree of differentiation, RAS mutations, and less lymph node metastasis." (PMID 33479369, 2021). "To clarify the potential mechanism by which MFN2 acts as a tumor suppressor in RAS-mutated thyroid cancer cells, we also evaluated the changes in the PI3K-AKT pathway." (PMID 33479369, 2021). "In our study, we tried to evaluate the role of MFN2 as a tumor suppressor in cell proliferation and cancer cell invasion in RAS mutated thyroid cancer cells because of a significant association of MFN2 expression with RAS like phenotype in mRNA expression." (PMID 33479369, 2021). "MFN2 overexpression also significantly decreased thyroid cancer cell invasion and migration by inhibiting EMT." (PMID 33479369, 2021). "Our results suggest that MFN2 plays an important role as a tumor suppressor in thyroid cancers by regulating EMT." (PMID 33479369, 2021). "To determine the clinical significance of MFN2 in human thyroid cancer, we performed an integrative analysis using TCGA-THCA data." (PMID 33479369, 2021). "The results of our study also suggest that MFN2 plays a role as a tumor suppressor in thyroid cancers by inhibiting AKT signaling." (PMID 33479369, 2021). "In conclusion, MFN2 was found to play an important role as a tumor suppressor in thyroid cancer progression and metastasis through modulating EMT and AKT signaling pathway." (PMID 33479369, 2021). "In our study, MFN2 modulated EMT in thyroid cancer by regulating the expression of EMT-related transcription factors at mRNA and protein levels." (PMID 33479369, 2021). "MFN2 might be an important prognostic marker of thyroid cancer and therapeutic target for its treatment based on its significant association with prognosis and LN metastasis in thyroid cancer." (PMID 33479369, 2021). "Therefore, we conducted functional study using thyroid cancer cells with RAS mutation (KRAS mutation in Cal62 and HRAS mutation in HTH83) because high MFN2 expressed PTC are related with RAS-like gene expression." (PMID 33479369, 2021). "We evaluated the prognostic impacts of MFN2 expression in thyroid cancer by analyzing TCGA data." (PMID 33479369, 2021). "In this study, we evaluated the potential role of MFN2 in thyroid cancer using TCGA data." (PMID 33479369, 2021). "In this study, we evaluated the potential roles of MFN2 in the progression of thyroid cancer." (PMID 33479369, 2021). "Thus, MFN2 acts as a tumor suppressor in thyroid cancer progression and metastasis by modulating EMT." (PMID 33479369, 2021). "Therefore, we evaluated the role of MFN2 as a tumor suppressor in thyroid cancer progression in the context of EMT." (PMID 33479369, 2021). "Here, we investigated the potential roles of Mitofusin-2 (MFN2) in thyroid cancer progression." (PMID 33479369, 2021). "Consequently, downregulation of MFN2 using CRISPR/Cas9 or siRNA increased thyroid cancer cell invasion and migration by inducing EMT, and this was associated with activation of the AKT signaling pathway." (PMID 33479369, 2021). "Mitofusin 2 (MFN2), a mitochondrial dynamin-like GTPase that regulates mitochondrial stability and cell metabolism, is expressed at low levels in aggressive thyroid cancer and correlates with BRAFV600E-like/low thyroid differentiation tumors." (PMID 35159110, 2022). "In vitro and in vivo, MFN2 was knocked out using CRISPR/Cas9 or siRNA, and MFN2 was stably overexpressed in two thyroid cancer cell lines (Cal62 and HTH83)." (PMID 33479369, 2021).
thyroid cancer (continued). "What we found in this study is that MFN2 can inhibits cancer cell invasion through inhibiting EMT process and MFN2 has limited effects of cell proliferation and tumor growth in thyroid cancer cell model." (PMID 33479369, 2021). "To confirm the effect of MFN2 on EMT, we evaluated the changes in the expression of EMT markers by overexpressing the gene in thyroid cancer cells." (PMID 33479369, 2021). "However, MFN2 can inhibit cancer cell invasion and EMT in thyroid cancer cells." (PMID 33479369, 2021). "However, MFN2 might play a limited role in suppressing ERK signaling in thyroid cancer cells, and this phenomenon might explain why there were no significant changes in cancer cell proliferation following the modulation of MFN2 expression." (PMID 33479369, 2021). "However, to our knowledge, currently there are no studies on the role of MFN2 in thyroid cancer." (PMID 33479369, 2021).
Vocal cord paralysis (3 papers, 2017 to 2021). A loss of the ability to move the vocal folds. "Additionally, vocal cord paralysis seen in the affected boy has been occasionally reported in CMT2A patients harboring MFN2 mutations." (PMID 34193129, 2021). "Two patients with MFN2 p.Arg364Trp mutation had vocal cord paralysis." (PMID 28660751, 2017). "Vocal cord paralysis has been reported as an early, severe and frequent symptom of GDAP1-associated neuropathy [CMT4A], often followed by diaphragmatic dysfunction, and in both AD and AR forms of CMT2A (mutations in the MFN2 gene)." (PMID 28190646, 2017).
ZIKV infection (3 papers, 2020 to 2025). "It has been demonstrated that during ZIKV infection the mitofusin 2 (MFN2) protein required to mediate mitochondrial fusion is reduced, and as such, mitochondria fragmentation is involved in the mitochondria apoptotic pathway observed in ZIKV infection." (PMID 35736984, 2022). "Although ZIKV infection still shortened mitochondrial branch length in cells overexpressing MFN1 or MFN2, the range of branch lengths in these cells was similar to uninfected controls." (PMID 33424801, 2020). "In this study, the lower levels of MFN2 after ZIKV infection implies a role for mitochondrial dysregulation in ZIKV-mediated microcephaly." (PMID 33424801, 2020). "We found that ZIKV infection disrupted mitochondrial dynamics, mitochondrial network structure, and function by decreasing MFN2 protein levels." (PMID 33424801, 2020). "ZIKV infection also decreased the levels of mitofusin 2, which modulates mitochondria fusion." (PMID 33424801, 2020). "This aligns with previous studies showing ZIKV infection induces mitochondrial fragmentation through the negative regulation of MFN2 expression, reducing mitochondrial fusion capacity." (PMID 41012699, 2025). "To further explore if blocking mitochondrial fragmentation would help increase cell survival after ZIKV infection, we over-expressed both MFN1 and MFN2 to restore normal fusion and treated cells with Mdivi-1 to inhibit DNM1L activity, reducing mitochondrial fission." (PMID 33424801, 2020). "However, a reduction of MFN2 mRNA was observed in the myeloid dendritic cells from ZIKV-infected patients, as well as the dendritic cells 24 h after infection in vitro, implying differential regulation of MFN2 expression in different types of host cells during ZIKV infection." (PMID 33424801, 2020). "The mitochondrial networks were only spared in MFN2 and not MFN1 overexpressing cells after ZIKV infection." (PMID 33424801, 2020).
acute liver failure (2 papers, 2017 to 2022). Rapid deterioration of liver function causing encephalopathy and coagulopathy. "Correlation analysis between haplotypes of MFN2 gene polymorphisms and the risk of acute liver failure." (PMID 28513770, 2017). "Comparison of liver functions in acute liver failure patients with different genotypes of MFN2 gene polymorphisms." (PMID 28513770, 2017). "Distribution of genotype and allele frequencies of MFN2 gene polymorphisms in acute liver failure patients and healthy participants." (PMID 28513770, 2017). "This study aimed to determine the role of mitofusin 2 (MFN2) gene polymorphisms in the risk and prognosis of acute liver failure (ALF)." (PMID 28513770, 2017). "For example, it has been found that in patients with slow plus acute liver failure, mitochondrial element 2 (mitofusin 2, MFN2) has a role in promoting mitochondrial outer membrane fusion and inner membrane docking, thereby increasing autophagy levels in hepatocytes and reducing apoptosis." (PMID 36438202, 2022).
asthma (2 papers, 2024 to 2025). "Prior research has indicated that the expression of mfn2 is diminished in human ASMCs associated with asthma, which correlates with an increase in mitochondrial fragmentation." (PMID 39382744, 2024). "In HDM induced AECs injury, there is a notable decrease in the expression of drp1 protein, increase in the expression of mfn2, which occurs prior to the production of pro-inflammatory cytokines in asthma." (PMID 39382744, 2024).
autism (2 papers, 2012 to 2019). Persistent deficits in social interaction and communication and interaction as well as a markedly restricted repertoire of activity and interest as well as repetitive patterns of behavior. "When we review the networks of genetic associations of the MFN2 gene, the integration with genes that are more likely to be associated with the development of autism is evident." (PMID 31018497, 2019). "In autism postmortem brains, the Anterior Cingulate Gyrus region-specific MFN2 gene shows downregulated expression." (PMID 31018497, 2019). "However, this last MFN2 gene was the only one that showed a significantly higher expression in children with autism." (PMID 31018497, 2019).
cataract (2 papers, 2018 to 2026). Partial or complete opacity of the crystalline lens of one or both eyes that decreases visual acuity and eventually results in blindness. "We suggest that genetic testing of Mfn2 mutations should be included for patients with a clinical diagnosis of congenital cataracts in the future to corroborate our findings in this animal study." (PMID 29367651, 2018). "Mfn2 CKO mice had postnatal congenital cataracts and microphthalmia compared to the control littermates." (PMID 29367651, 2018). "In summary, this morphologic study provides the first direct genetic evidence of the role of Mfn2 in congenital cataracts and microphthalmia, delineating the distinct function of Mfn2 in regulating lens growth and development." (PMID 29367651, 2018). "Mfn2 conditional knockout also leads to abnormal apoptosis of LECs and thus induces cataracts." (PMID 29367651, 2018). "Herein, we demonstrate in mice that an Mfn2 gene conditional knockout could lead to congenital cataracts due to mitochondrial dysfunction in lens cells." (PMID 29367651, 2018). "Enucleated eyes of Mfn2 CKO mice at 1 month after birth showed consistent microphthalmia comparing to the eyes of control littermates, and nearly 84% developed cataracts." (PMID 29367651, 2018). "Examination of eye specimens from the Mfn2 CKO mice from E14 to 12 weeks (N = 32) revealed that microphthalmia and cataracts were not severe during the embryo stage, but obvious after delivery and progressively worsened with age." (PMID 29367651, 2018).
Charcot-Marie Tooth neuropathy (2 papers, 2016 to 2022). "GDAP1 and MFN2 are outer mitochondrial membrane (OMM) proteins and both are related to Charcot-Marie Tooth neuropathy." (PMID 35177962, 2022).
chronic heart failure (2 papers, 2012 to 2025). "In contrast, chronic heart failure (HF) involves MAM uncoupling due to reduced expression or dysfunction of tethering proteins such as mitofusin-2 (MFN2) and FUNDC1, impairing Ca2+ signaling, mitophagy, and bioenergetics." (PMID 41294815, 2025).
chronic kidney disease (2 papers, 2012 to 2025). Impairment of the renal function secondary to chronic kidney damage persisting for three or more months. "We are therefore unable to study the susceptibility of MFN2 cKO to acute or chronic kidney disease." (PMID 22292091, 2012).
chronic obstructive pulmonary disease (2 papers, 2023 to 2024). A chronic and progressive lung disorder characterized by the loss of elasticity of the bronchial tree and the air sacs, destruction of the air sacs wall, thickening of the bronchial wall, and mucous accumulation in the bronchial tree. "This is supported by findings in chronic obstructive pulmonary disease studies where Leflunomide recovered MFN2 expression previously reduced in lung tissues and alveolar cells exposed to cigarette smoke extract (CSE)." (PMID 38607070, 2024).
colon cancer (2 papers, 2021 to 2024). "Low MFN2 expression was observed in colon cancer, and high MFN2 expression has been associated with a better prognosis." (PMID 39273403, 2024).
energy metabolism disorder (2 papers, 2021 to 2024). "At present, the mechanism of central nervous system involvement of CMT2A2 is still unclear, which is speculated to be related to mitochondrial energy metabolism disorder in the brain caused by MFN2 mutation." (PMID 38183043, 2024).
epilepsy (2 papers, 2024 to 2025). A brain disorder characterized by episodes of abnormally increased neuronal discharge resulting in transient episodes of sensory or motor neurological dysfunction, or psychic dysfunction. "Therefore, demethylating agents could restore MFN2 function and improve cognitive deficits, providing a potential therapeutic avenue for epilepsy treatment." (PMID 41456957, 2025). "Therefore, targeting Drp1 and MFN2 may be novel therapeutic strategies for epilepsy management, offering insights into how modulating mitochondrial dynamics can influence neuronal survival and function during epileptic events." (PMID 41456957, 2025).
familial Alzheimer disease (2 papers, 2018 to 2022). A degenerative disease of the brain that causes gradual loss of memory, judgment, and the ability to function socially. "Presenilin 2 (PS2) mutations underlie familial Alzheimer’s disease (FAD) by promoting ER-mitochondria coupling only in the presence of Mfn2." (PMID 35625553, 2022). "Mfn2 and the Familial Alzheimer’s Disease (FAD)-related protein Presenilin-2 (PS2) have been reported to act in a common route to tune the ER–mitochondria interface." (PMID 29229997, 2018).
Hyperinsulinemia (2 papers, 2014 to 2022). An increased concentration of insulin in the blood. "In this study, we used phosphorylated DRP1 at Ser616 (p-DRP1 S616) and MFN2 as the marker of fission and fusion to examine the effects of hyperinsulinemia on the mitochondrial dynamics in microglia by Western blot." (PMID 36466168, 2022). "The results showed that p-DRP1 S616 was significantly increased, contrary MFN2 expression was decreased in both BV2 cells and primary microglia treated by insulin, suggesting hyperinsulinemia made mitochondrial fission and fusion out of balance in microglia." (PMID 36466168, 2022). "Our results showed that hyperinsulinemia decreased membranous expression of GLUT4, and impaired mitochondrial function indicated by increased phosphorylation of dynamin-related protein 1 (DRP1) at Ser616 and decreased Mitofusin 2 (MFN2) protein expression." (PMID 36466168, 2022).
Hypoglycemia (2 papers, 2021 to 2025). A decreased concentration of glucose in the blood. "Here, the densitometric analysis of blots revealed a trended increase in the protein levels of Mfn2 in the hyperglycemic group, whereas recurrent hypoglycemia tended to decrease the activation of mitochondrial fission protein pDRP1 when compared to the hyperglycemic animals." (PMID 34948265, 2021).
influenza (2 papers, 2020 to 2022). An acute viral infection of the respiratory tract, occurring in isolated cases, in epidemics, or in pandemics; it is caused by serologically different strains of viruses (influenzaviruses) designated A, B, and C, has a 3-day incubation period, and usually lasts for 3 to 10 days. "In addition, Mfn2 binds to NLRP3 to promote IL-1β secretion after infection with RNA viruses, including influenza, measles, or EMCV." (PMID 35958608, 2022).
kidney damage (2 papers, 2020 to 2023). "Loss of Mfn2 stimulates the Rsa/ERK pathway, thereby increasing the proliferation of renal tubular epithelial cells and alleviating I/R-induced kidney damage." (PMID 37635869, 2023). "Melatonin improved nephropathy of ZDF rats and modulated their mitochondrial dynamics by reducing expression of Drp1 fission marker and increasing that of fusion markers, Mfn2 and Opa1." (PMID 32927647, 2020). "Based on previous studies, it was initially expected that the absence of Mfn2 would exacerbate kidney damage in the I/R model." (PMID 37635869, 2023).
left ventricular hypertrophy (2 papers, 2016 to 2022). Enlargement of the LEFT VENTRICLE of the heart. "Postnatal IH causes mitochondrial fission by decreasing the expression of Mfn2 and increasing the expression of mitochondrial fission protein in cardiomyocytes, which leads to left ventricular hypertrophy and impaired contractile function in male rats." (PMID 35600069, 2022).
Leigh syndrome (2 papers, 2016 to 2023). A progressive neurological disease defined by specific neuropathological features associating brainstem and basal ganglia lesions. "Given that mutations in LRPPRC result in Leigh syndrome, it is likely that Ben/Ubc13-PINK1-Park may regulate Mfn1 and Mfn2 in Leigh syndrome as well in other mitochondrial diseases." (PMID 37098042, 2023).
liver cirrhosis (2 papers, 2016 to 2022). "Rat HSC-T6 HSC were cultured and transfected by adenovirus- (Ad-) Mfn2 or its negative control (NC) vector (Ad-green fluorescent protein (GFP)); a rat liver cirrhosis model was established via subcutaneous injection with carbon tetrachloride (CCl4)." (PMID 35083025, 2022).
liver failure (2 papers, 2021 to 2025). A liver disease characterized by the liver losing or has lost all of its function. "In acute or chronic liver failure, studies have found that Mfn2 can significantly attenuate the symptoms of liver failure, improve the expression of autophagy related proteins, and downregulate the expression of apoptosis-related proteins through the PI3K/Akt/mTOR signaling pathway." (PMID 40362804, 2025). "We chose to analyze MFN2 because it has also been suggested that MFN2 is a protective target in the liver, as it controls the physiological balance between apoptosis and autophagy in liver failure." (PMID 34822661, 2021).
lymph node metastasis (2 papers, 2016 to 2021). "Furthermore, circ-MFN2 was also significantly upregulated in the tissues of the advanced stage of CRC patients (III-IV) and those with lymph node metastasis (Yes)." (PMID 34093664, 2021).
male infertility (2 papers, 2021 to 2022). The inability of the male to effect fertilization of an ovum after a specified period of unprotected intercourse. "We previously revealed that either Mfn1 or Mfn2 conditional knockout in early germ cells resulted in male infertility." (PMID 34948301, 2021). "Another study, relating to testicular damage caused by Cadmium (Cd) also found that an intraperitoneal injection of Cd into rats resulted in reproductive toxicity, including poor semen quality, male infertility, and reduced expression levels of mRNA for both Mfn1 and Mfn2." (PMID 35725948, 2022). "However, the intraperitoneal injection of vitamin E improved the mRNA expression levels of Mfn1 and Mfn2, thus improving Cd-induced poor semen quality and male infertility." (PMID 35725948, 2022).